CDH11 (cadherin 11)
Diseases named in the same sentence as CDH11 in open-access papers (continued):
Sharing a sentence is not in itself a finding about the gene and the disease.
osteosarcoma (13 papers, 2005 to 2025). A usually aggressive malignant bone-forming mesenchymal neoplasm, predominantly affecting adolescents and young adults. "The loss or decrease of CDH11 expression plays an important role in osteosarcoma metastasis." (PMID 23971040, 2013). "In the case of module 3 genes associated with osteosarcoma, eight are found in COSMIC (LUM, COL6A3, TNC, CALU, COL16A1, OMD, ITGB5, and DPSYL3), and two (CDH11 and OMD) are oncogenes found in OncoKB." (PMID 34570764, 2021). "The involvement of CDH11 in tumorigenesis was initially indicated by the observation that CDH11 was overexpressed in various cancer types including breast, prostate, osteosarcoma and colon cancers." (PMID 24810778, 2014). "Several studies have suggested that CDH11 displays tumor suppressor properties in osteosarcomas and other tumors." (PMID 23971040, 2013). "FGFR1 and CDH11 are markers of osteoclasts or osteosarcoma cells." (PMID 38218960, 2024). "FGFR1 and CDH11 were mainly expressed on 8 clusters of cells, thus it could be determined that the 8 clusters were osteoblasts or osteosarcoma cells." (PMID 38218960, 2024). "However, the rate of expression of CDH11 in osteosarcomas was reduced compared to osteochondromas to 40.0% (36/90)." (PMID 23971040, 2013). "Furthermore a higher level of expression of OB-cadherin/CDH11 has been correlated with increased patient survival in osteosarcoma." (PMID 23352643, 2013). "As part of ongoing efforts to understand the roles of and interactions between CD44V6, CDH11, and β-catenin in osteosarcomas, we report in this study our findings regarding the immunohistochemical expression and clinicopathological features of these biomarkers in human osteosarcomas." (PMID 23971040, 2013). "It has been indicated that CDH11 expression may be useful as a prognostic marker of disease progression and survival in osteosarcomas." (PMID 23971040, 2013). "As CDH11-overexpressing osteosarcoma cells have been found to exhibit a marked reduction in their ability to form pulmonary metastasis, a downregulation of CDH11 may be one mechanism by which growth factors contribute to tumour progression." (PMID 15846300, 2005). "However, the expression rate of CDH11 in osteosarcomas was reduced to 40.0% (36/90)." (PMID 23971040, 2013). "Consequently, it appears that CDH11 may be involved in osteosarcoma invasion and metastasis through a potential link between inflammation and tumor development." (PMID 23971040, 2013). "Thus, our results indicated abnormal expression of CD44V6, CDH11, and β-catenin in osteosarcomas and osteochondromas, which may provide important indicators for further research." (PMID 23971040, 2013). "Further, three previously identified potential gene targets of ACT for osteosarcoma, including CADM1, CDH11, and MMP14, also showed high protein expression in osteosarcoma compared with normal adjacent tissues." (PMID 37457661, 2023). "A multivariate analysis performed on 90 osteosarcomas and 20 osteochondromas, indicated the clinical stage, metastasis status, and the relationship between the expression of CD44V6, CDH11, and β-catenin correlated with improved outcome." (PMID 35785191, 2022). "For example, the epithelial markers such as cadherin-11 and autocrine motility factor/ phosphoglucose isomerase (AMF/PGI) were expressed in osteosarcoma." (PMID 28938584, 2017). "More recently, the expression of certain biological molecules has been identified as potential prognostic markers for osteosarcoma metastasis, including the expression of CD44V6, CDH11, and β-catenin." (PMID 23971040, 2013). "Furthermore, Cadherin-11 (CDH11), a marker of MET in osteosarcoma, was upregulated in 143BGBM and 143BNSC tumours, indicating partial differentiation and metastasis." (PMID 27551510, 2016). "E-cadherin is not highly expressed in osteosarcoma cells, however Snail2 may also regulate expression of other cadherins, such as mesenchymal cadherin (OB-cadherin/CDH11), known to be expressed in osteosarcomas." (PMID 23352643, 2013).
pancreatic cancer (12 papers, 2014 to 2025). "The set of immune cell signatures identified in Cdh11-deficient mice may represent hallmarks of positive disease prognosis in pancreatic cancer, and maybe other solid tumors such as breast, head and neck and colorectal cancers." (PMID 37954069, 2023). "Similar to BC, breast and pancreatic cancer cell lines are also largely unaffected by CDH11 according to DepMap." (PMID 41263259, 2025). "There are several reports that CDH11 promotes metastasis and progression of breast and pancreatic cancers, and CDH11 has been reported to be highly expressed in muscle‐invasive BC." (PMID 41263259, 2025). "Cadherin-11 is necessary for metastatic spread in breast and pancreatic cancers, and it is remarkable that both CDH2 and CDH11 were increased in normal epithelial cells." (PMID 38473331, 2024). "CDH11 is also involved in the activation of pancreatic stellate cells (PSCs) and migration of pancreatic cancer cells." (PMID 33442417, 2021). "Elimination or inhibition of CDH11 (expressed by CAFs in the pancreatic tumor stroma) can reduce the growth of pancreatic tumors and enhance their response to gemcitabine by sc-RNA." (PMID 34895349, 2021). "With Oncomine, compared with normal tissues, a high level of CDH11 expression was observed in breast, colorectal, esophageal, gastric, liver, lymphoma, pancreatic cancer, and sarcoma tissues." (PMID 32685527, 2020). "Cadherin-11 is a cell surface marker up-regulated in activated PSCs and is involved in pancreatic cancer migration." (PMID 29967585, 2018). "Furthermore, dual cadherin antibodies recognizing CDH1 (epithelial E‐cadherin) and CDH11 (mesenchymal OB‐cadherin) have been reported to target circulating tumor cells and inhibit bloodborne metastasis in breast and pancreatic cancers." (PMID 41263259, 2025). "Using single-cell RNA sequencing (scRNA-seq) we compared the tumor microenvironment of Cdh11-deficient (KPC-Cdh11+/-) and wildtype (KPC-Cdh11+/+) mice with pancreatic tumors and identified immune subpopulations that correlate with decreased tumor burden and improved survival." (PMID 37954069, 2023). "Next, we analyzed publicly available human pancreatic cancer data (data from CPTAC) and found that CDH11 protein expression was significantly elevated in tumor samples compared to normal." (PMID 37954069, 2023). "CDH11 plays an inflammation-inducing role in EMT and is involved in progression from chronic pancreatitis to pancreatic cancer 3,49." (PMID 33442417, 2021). "More recently, the aberrant expression of P-cadherin (CDH3) and cadherin-11 (CDH11) have also been described in the context of different types of cancer such as in malignant melanoma, breast, gastric, lung, colorectal, and pancreatic cancer." (PMID 31373305, 2019). "CDH11 promotes immunosuppression and ECM deposition in pancreatic cancer." (PMID 41263259, 2025). "However, the Cdh11 inhibitor, was ineffective in reducing tumor burden of mT3 pancreatic tumor bearing immunosuppressed Rag1-mutant mice, suggesting that T and B cells are required for immunomodulation of PDAC mediated by Cdh11 inhibition." (PMID 37954069, 2023).
retinoblastoma (11 papers, 2010 to 2025). A malignant tumor that originates in the nuclear layer of the retina. "Such is the case for retinoblastoma, where CDH11 undergoes genomic deletions 26 and its loss correlates with increased invasive phenotypes in cancer cells." (PMID 22374749, 2012). "One of these changes is genomic loss of the CDH11 gene, suggesting that this gene normally suppresses the development of retinoblastoma." (PMID 20421947, 2010). "Our results indicate that when Cdh11 alleles are mutated in TAg-RB mice, fewer cells express TAg and develop into retinoblastoma." (PMID 20421947, 2010). "Similarly, loss of CDH11 tumor suppressor gene shows the highest frequency in retinoblastoma tumors." (PMID 21134280, 2010). "Although fewer multifocal tumors initiate in mice with mutant Cdh11 alleles, suggesting that Cdh11 loss modulates the number of TAg-espressing cells in this murine model, the resulting tumors grow faster, describing a tumor suppressor role for Cdh11 in retinoblastoma progression." (PMID 20421947, 2010). "CDH11, for example, was upregulated and is a candidate tumor suppressor gene whose expression is frequently lost in advanced retinoblastoma." (PMID 33270844, 2020). "In murine retinoblastoma, CDH11 functions as a tumor suppressor, and overexpression of the gene in mouse models resulted in increased cell death." (PMID 33192560, 2020). "It was shown that inactivation of CDH11 in murine retinoblastoma accelerated tumor growth validating its retinoblastoma suppressive function." (PMID 27126562, 2016). "CDH11 gene copy number and expression are frequently lost in human retinoblastomas and in retinoblastomas arising in TAg-RB mice." (PMID 20421947, 2010). "To examine the tumor suppressor role of Cdh11 in retinoblastoma development, we crossed Cdh11-/- mice with TAg-RB mice and analyzed genotypes Cdh11+/+;TAg+/-, Cdh11+/-;TAg+/-, and Cdh11-/-;TAg+/-, on a mixed 129/C57Bl-6 background." (PMID 20421947, 2010). "We showed that Cdh11 is a suppressor of retinoblastoma progression by using a unique and highly sensitive method to identify and quantify tumor volume." (PMID 20421947, 2010). "Based on the location of these genomic changes, potential oncogenes (KIF14, E2F3 and DEK) and tumor suppressor genes (p75NTR and CDH11) have been identified and shown to have involvement in retinoblastoma development and progression." (PMID 20421947, 2010). "In order to understand the role of Cdh11 in retinoblastoma progression, we examined its presence during healthy retinal development." (PMID 20421947, 2010). "Taken together, these data provide substantial evidence to suggest that in retinoblastoma Cdh11 acts as a tumor suppressor by facilitating cell death." (PMID 20421947, 2010). "We present novel data indicating that Cdh11 functions as a tumor suppressor gene in retinoblastoma by facilitating cell death." (PMID 20421947, 2010). "Similarly, in vitro and in vivo studies of murine retinoblastoma, cdh11 acted as a tumor suppressor gene through promotion of tumor cell death." (PMID 30691241, 2019). "We now address the roles of Cdh11 in developing retina and retinoblastoma." (PMID 20421947, 2010). "In summary, we describe a mechanism by which Cdh11 may be functioning as a tumor suppressor gene in retinoblastoma." (PMID 20421947, 2010). "We now confirm the tumor suppressor role Cdh11 in retinoblastoma through functional experiments." (PMID 20421947, 2010). "In our present study, we use the TAg-RB retinoblastoma mouse model to study the function of Cdh11 in tumorigenesis." (PMID 20421947, 2010).
invasive breast carcinoma (10 papers, 2014 to 2025). A carcinoma that infiltrates the breast parenchyma. "CDH11 is up-regulated in diseases associated with excess ECM deposition such as invasive breast cancer, scleroderma, and liver fibrosis." (PMID 35573666, 2022). "Therefore, the present study by using public cancer databases and analytical tools, consistent with our previous findings, demonstrate that elevated CDH11 mRNA level is associated with invasive breast carcinoma as compared to normal breast tissue." (PMID 31248373, 2019). "For instance, cadherin 11 is often overexpressed in invasive breast cancer cells; inhibiting cadherin 11 can reduce tumor cell migration and invasion in vitro and diminish tumorigenicity and growth in mouse models." (PMID 40502441, 2025). "A cell adhesion molecule called CDH11, which is overexpressed in human invasive breast carcinoma tissue compared to normal breast tissue, is expressed in the bone microenvironment." (PMID 36686653, 2022). "CDH11 overexpression is seen in invasive breast carcinomas and bone metastatic lesions but conversely high expression has been correlated with improved prognosis in human OSA." (PMID 33556121, 2021). "Having established a role for CDH11 in the oncogenicity and progression of invasive breast cancer, we explored its therapeutic targetability of CDH11 and the probable anti-metastatic effect of same, using anti-CDH11 antibody." (PMID 31248373, 2019). "In the present study, for the first time, to the best of our knowledge, we demonstrated that CDH11 is an independent prognosticator of poor clinical outcome and a regulator of the metastatic phenotype in invasive breast cancer." (PMID 31248373, 2019). "In this study, we highlight the role of CDH11 in invasive breast cancer metastatic and CSC-like phenotype, as well as showcase the miR-335-mediated therapeutic efficacy of anti-CDH11 antibody treatment." (PMID 31248373, 2019). "In this study, we demonstrated for the first time that ILF3 interacted with HOXC8 to activate CDH11 transcription in invasive breast cancer cells." (PMID 29296180, 2017). "We previously reported that knockdown of HOXC8 led to the reduction in CDH11 expression in invasive breast cancer cells." (PMID 24810778, 2014). "CDH11 is increased in invasive breast cancers and in DCIS when compared to normal tissue." (PMID 24681547, 2014). "CDH11 is markedly elevated in the stroma of invasive breast cancers compared to normal stroma." (PMID 24681547, 2014). "For example, CDH11 is only expressed in invasive breast cancer cells while is absent in non-invasive ones." (PMID 24810778, 2014). "As not all DCIS lesions are CDH11 positive and high expression occurs in comedo type DCIS, a subclass with greater risk of recurrence, CDH11 positive lesions may be more likely to develop into invasive breast cancer." (PMID 24681547, 2014).
melanoma (10 papers, 2012 to 2024). A malignant, usually aggressive tumor composed of atypical, neoplastic melanocytes. "In our models and tumour types (head and neck and melanoma), the functional consequence of CDH11 loss-of-expression is an enhanced metastatic phenotype, as we have demonstrated experimentally." (PMID 22374749, 2012). "In head and neck and melanoma, loss of CDH11 expression enhanced the metastatic phenotype 24." (PMID 33391403, 2021). "Low expression of CDH11 was observed in melanoma (n = 6, M.S. = 100), adenocarcinoma (n = 49, M.S. = 81) and carcinoid tumors (n = 14, M.S. = 72)." (PMID 37558205, 2023). "When we analysed a collection of non-cultured tumourigenesis samples from head and neck cancer and melanoma patients, we observed CDH11 hypermethylation in 19% (13 of 68) and 16% (8 of 51) of cases, respectively." (PMID 22374749, 2012). "Deregulation of cadherin-11 observed in melanoma is an indirect consequence of decrease in miR-196a expression." (PMID 21860617, 2012). "Also in melanoma, we showed that silencing of cadherin-11 (CDH11) occurs essentially in the lymph node metastases, suggesting a metastasis-specific role of this epigenetic event." (PMID 37369946, 2023). "We found that CDH11 DNA methylation-associated transcriptional silencing occurred in the corresponding lymph node metastases of melanoma and head and neck cancer cells but not in the primary tumours." (PMID 22374749, 2012). "Mueller and Bosserhoff showed that cadherin-11 expression is also lost in melanoma cells." (PMID 21860617, 2012). "Melanoma cells do not undergo normal EMT changes, however they utilize EMT and MET (mesenchymal-to-epithelial transition) states that are mediated by adhesion molecules such as Cadherin-11, Connexis, integrins, N-cadherin and MCAM (CD146) which all are indicators of progressed melanoma." (PMID 35127523, 2021).
breast tumor (8 papers, 2013 to 2023). "Within the breast tumor cells, a higher CDH11 level was detected in the nucleus when compared with the cytoplasm (nucleus M.S. = 86.38 vs. cytoplasm M.S. = 61.28, n = 219, P < 0.0001)." (PMID 37558205, 2023). "CDH11 has been documented to be preferentially expressed in clinical specimens of malignant when compared with non‐malignant breast tumor or normal tissue." (PMID 37558205, 2023). "Analysis of breast tumor sample microarray database reveals that the expression HOXC8 and CDH11 are in a strong positive linear association." (PMID 24810778, 2014). "Strong correlation between HOXC8 and CDH11 expression in clinical breast tumor specimens is also in agreement that HOXC8 is a CDH11 transcription factor." (PMID 24810778, 2014). "The analysis of publically available human breast tumor microarray gene expression database demonstrates a strong positive linear association between HOXC8 and CDH11 expression (ρ = 0.801, p < 0.001)." (PMID 24810778, 2014). "Moreover, breast tumor cells exhibited an elevated CDH11 expression level when compared with the surrounding stroma cells (tumor M.S. = 86.4 vs. stroma M.S. = 65.9, n = 219, P < 0.0001)." (PMID 37558205, 2023). "Given that β‐catenin is a classical CDH11 intracellular binding partner at the cell surface, we investigated whether β‐catenin and CDH11 co‐localized in the nucleus of cells in the breast tumor clinical samples." (PMID 37558205, 2023). "PKF118–310 inhibits the self-renewal of breast tumor-initiating cells by Wnt/β-catenin signaling and CDH11 was found to inhibit actin stress fiber formation, thus, further inhibiting tumor cell migration and invasion via the regulation of Wnt/β-catenin signaling." (PMID 24932283, 2014). "For examples, fibroblast-like synoviocytes can migrate and invade into pigmented villonodular synovitis by expressing CDH11 63, Silencing of CDH10 was also found as another mechanism to enhance breast tumor cell mobility in hypoxic conditions." (PMID 33204327, 2020).
glioblastoma (8 papers, 2013 to 2025). The most malignant astrocytic tumor (WHO grade IV). "Interestingly, elevated expression of CDH11 has been observed in glioblastoma and has been associated with increased cell migration." (PMID 34135003, 2021). "Another gene from the DEG list is Cadherin-11 (CDH11), which has been shown to promote migration of glioblastoma cells." (PMID 27791206, 2016). "LN229 cells are glioblastoma cell lines that express both mesenchymal cadherins (CDH11 and N-cadherin)." (PMID 24681547, 2014). "Together, these findings show that Cadherin-11 can promote cell migration in neural precursors and glioblastoma cells and suggest that endothelial cells increase tumor aggressiveness by co-opting mechanisms that regulate normal neural development." (PMID 23951053, 2013). "TGFβ promotes glioblastoma cell motility, and knockdown of CDH11 expression in primary human glioblastoma cells inhibits TGFβ-stimulated migration." (PMID 23951053, 2013). "To examine the cellular expression of CDH11 in human glioblastoma, we performed immunoperoxidase staining for CDH11 on human tumor samples." (PMID 23951053, 2013). "Interestingly, the growth and migration of LN229 glioblastoma cells were more sensitive to CDH11 than N-cadherin knockdown." (PMID 24681547, 2014). "In glioblastoma, CDH11-expressing tumor cells can be found localized near tumor vasculature." (PMID 23951053, 2013). "Endothelial cells stimulate TGFβ signaling and CDH11 expression in glioblastoma cells." (PMID 23951053, 2013). "CDH11 is expressed in breast cell lines characterized as Basal B, as well as poor prognosis malignancies including glioblastoma multiforme for which no effective treatment exists." (PMID 24681547, 2014).